AHR (aryl hydrocarbon receptor)
Diseases named in the same sentence as AHR in open-access papers (continued):
Sharing a sentence is not in itself a finding about the gene and the disease.
endometrial cancer (8 papers, 2012 to 2025). Primary or metastatic malignant neoplasm involving the endometrium (mucous membrane that lines the endometrial cavity). "In a previous in vitro study, AHR_1 was found to regulate AHR-transcription in a polymorphism-dependent manner via the tumour suppressor nuclear factor 1-C (NF1C) in endometrial cancer." (PMID 40646277, 2025). "Some studies suggest AhR plays an oncogenic role in endometrial cancer, as AhR is upregulated in human endometrial cancer lesions and its increased expression significantly correlates with higher tumor grade." (PMID 38807762, 2024). "In summary, most of the data support inhibitory AhR–ERα crosstalk, where the activation of the AhR inhibits ERα signaling, leading to the inhibition of breast and endometrial cancer cell proliferation, survival, migration/invasion, and metastasis." (PMID 39339278, 2024). "In endometrial cancer, mixed observations regarding the tumor regulatory role of AhR have been reported." (PMID 38807762, 2024). "In the endometrial cancer cell, AR-QS but not AR-QL interacts with the anyl hydrocarbon receptor (AhR) bound to benzo [a] pyrene, an environmental factor, and enhances cancer growth." (PMID 38890503, 2024).
eosinophilia (8 papers, 2014 to 2025). "In another study using ovalbumin-induced airway allergy, systemic injection of high doses of the AhR agonist FICZ reduced eosinophilia and Th2 cytokines in the lung and blood IgE levels." (PMID 37190854, 2023). "After OVA challenge, absence of AhR was associated with significantly enhanced eosinophilia and lymphocyte influx into the airways of Ahr−/− mice." (PMID 34744763, 2021). "Our novel results show that expression of the AhR had minimal effect on Cl2-induced neutrophilia, but attenuated OVA-induced pulmonary inflammation that is typified by eosinophilia." (PMID 34744763, 2021).
heart failure (8 papers, 2015 to 2025). Inability of the heart to pump blood at an adequate rate to meet tissue metabolic requirements. "In addition, gut microbiota‐derived kynurenine, a metabolite associated with heart failure, also contributes to the progression of myocardial fibrosis through AhR activation." (PMID 40027477, 2025). "In analogy to human CHD, the congenital heart defects induced by AHR disruption in the mouse embryo may be a cause of cardiac insufficiency in the adult." (PMID 26555816, 2015). "However, activation of the AhR with subsequent induction of antioxidative defense mechanisms reduced heart failure in hypertensive rats." (PMID 34979820, 2022). "Strong induction of AhR detoxifying systems are not only energetically costly for organisms but also might be responsible for cardiac failure in larvae after oil exposure." (PMID 30332409, 2018). "Taken together, these data suggest that in vitro and in vivo AHR disruption-related effects have the potential to impair postnatal cardiovascular maturation and function, in analogy to the adult cardiac insufficiency resulting from congenital heart disease in humans." (PMID 26555816, 2015). "Although the connections between AHR transcriptional activation and the down-regulation of cardiac genes corresponding to embryo/larval heart failure have not been identified, AHR-driven cardiotoxicity is clearly mediated by transcription." (PMID 26658479, 2015).
injury (8 papers, 2021 to 2025). Damage inflicted on the body as the direct or indirect result of an external force, with or without disruption of structural continuity. "Taken together, these findings suggest the involvement of SULT1A1 and IS in the progression or deterioration of cisplatin-induced kidney injury via the cisplatin/IS/AhR/ROS axis." (PMID 33578912, 2021). "Taken together, these data suggest that miR-29b-2-5p may regulate the balance of Th17/Th22 subsets during acute lung injuries by altering AhR mRNA, which thereby alters the expression of IL-22 and RORc." (PMID 36809070, 2023). "Likewise, while the outcome of AHR activation in acute acetaminophen-liver injury is exacerbation of liver damage, AHR ligands seem to have beneficial effects in ethanol-induced liver injury." (PMID 34075438, 2021).
malignant glioma (8 papers, 2010 to 2025). A grade III or grade IV glioma arising from the central nervous system. "Kyn has been indicated to be responsible for tumor spheroids and the motility of malignant glioma cells by activating aryl hydrocarbon receptor (AhR) receptor and related signaling pathwasy." (PMID 27050278, 2016). "It has also been suggested that AHR is a promising target of anticancer therapy and can modulate survival and invasiveness of malignant glioma." (PMID 20664703, 2010). "Collectively, while these studies demonstrate the importance of AhR in malignant gliomas, more research is needed to understand its tumor modulatory roles that may shed light into contradictory data reported by different laboratories." (PMID 38807762, 2024). "In addition, certain cancer types can escape from immune recognition via an AhR pathway, as shown in malignant gliomas by Opitz and colleagues." (PMID 29487603, 2018). "AhR activity positively controls the levels of TGF-β1, TGF-β2, and latent TGF-β–binding protein 1 in malignant glioma cells." (PMID 32325928, 2020). "In contrast, some other studies suggest that constitutive AhR activity positively controls TGFβ1, TGFβ2, and LTBP-1 in malignant glioma cells." (PMID 24795504, 2014).
membranous nephropathy (8 papers, 2025 to 2026). "Research indicates that Lactobacillus can improve membranous nephropathy by inhibiting the aryl hydrocarbon receptor pathway." (PMID 39861454, 2025). "Research indicates that Lactobacillus can decrease the urinary total protein, urinary protein/creatinine (P/C) ratio, and urine albumin excretion rate, and improve membranous nephropathy by inhibiting the aryl hydrocarbon receptor pathway." (PMID 39861454, 2025). "Research on gut microbial metabolites indicates that Lactobacillus species can ameliorate membranous nephropathy by modulating tryptophan-derived indole metabolites to suppress the aryl hydrocarbon receptor pathway." (PMID 40568201, 2025). "As Lactobacillus species has been identified as a method to improve the prognosis of membrane nephropathy via activation of the intrarenal AhR signaling pathway, it could be deemed as a potential treatment regimen for DKD." (PMID 41140685, 2025). "Similarly, indole metabolites produced by tryptophan metabolism were found to ameliorate renal injury by antagonizing AHR activity as well in a model of membranous nephropathy (MN)." (PMID 40371325, 2025). "Additionally, using specific Lactobacillus strains, such as Lactobacillus reuteri, can improve membranous nephropathy by affecting the aryl hydrocarbon receptor pathway." (PMID 40703651, 2025). "Similarly, in membranous nephropathy, Moshen granule treatment alleviated kidney injury by activating the aryl hydrocarbon receptor (AhR), which upregulated Nrf2 and subsequently enhanced MnSOD expression, reducing oxidative stress and inflammation." (PMID 40722952, 2025).
multiple myeloma (8 papers, 2013 to 2024). "An earlier study had reported that the anti-myeloma effect of CLF was due to its inhibition of the AHR-polyamine metabolism axis." (PMID 35646666, 2022). "Relative AHR expression (ΔCt) in the myeloma lines was calculated following normalization with Beta-Actin (housekeeping gene)." (PMID 35646666, 2022). "We evaluated AHR expression using qRT-PCR (TaqMan Real-Time PCR Assays) in 10 myeloma cell lines and compared AHR expression with CLF cytotoxicity." (PMID 35646666, 2022). "Microarray analysis of 1,036 human cancer cell lines revealed a significant role of AhR in myelomas and other B lineage cancer subtypes among other cancers." (PMID 25669983, 2015). "Future work exploring the implications of AhR signaling and its role in the pathogenesis, immune response, and etiology of multiple myeloma and its precursor conditions (monoclonal gammopathy of undetermined significance (MGUS)) and smoldering myeloma (SMM) is warranted." (PMID 37958428, 2023). "In addition, the FDA-approved AHR antagonist clofazimine showed high efficacy in a transgenic model of multiple myeloma." (PMID 34572746, 2021). "Preclinical studies in multiple myeloma, suggest that therapeutic targeting of the AHR, with an inhibitor such as the FDA-approved clofazimine, may improve clinical outcomes." (PMID 34025677, 2021).
myocardial infarction (8 papers, 2017 to 2025). Gross necrosis of the myocardium, as a result of interruption of the blood supply to the area, as in coronary thrombosis. "Another study has shown that activating AHR can inhibit myocardial cell apoptosis, thereby alleviating cardiac remodeling and dysfunction in rats with myocardial infarction." (PMID 40863131, 2025). "The activation of AHR during myocardial infarction can regulate immune responses, reduce infarction area, and improve left ventricular ejection fraction." (PMID 40863131, 2025). "Currently, there are few experimental studies aimed at deeper elucidation of the cellular and molecular mechanisms behind the interaction of KP metabolites with AhR in cardiac tissues affected by myocardial infarction." (PMID 39000041, 2024). "Because of few data on the mechanisms of action of AhR in myocardial infarction, there is an urgent need to unravel the role of AhR signaling pathway during the heart injury." (PMID 34830207, 2021). "Moreover, expression of AhR increases in necrotic myocardium after myocardial infarction induced by LAD ligation." (PMID 34830207, 2021). "Indeed, myocardial infarction induced AhR and AhR-regulated IL-1β and IL-6 in mice heart and a natural flavone baicalin was able to inhibit the myocardial injury and inflammation by decreasing the expression of AhR." (PMID 34830207, 2021). "After myocardial infarction, KYN induces cardiomyocyte apoptosis through the production of reactive oxygen species via an AhR-dependent mechanism." (PMID 39000041, 2024). "A recent report has also described that CD69+ Tregs, through an AHR-dependent mechanism, express high levels of membrane CD39 in hypoxic conditions after myocardial infarction (MI)." (PMID 37223078, 2023). "The AHR agonist ITE mitigates cardiomyocyte apoptosis by activating the Akt/p70S6K signaling pathway, thereby attenuating left ventricular remodeling and improving cardiac dysfunction following myocardial infarction." (PMID 38879491, 2024). "Furthermore, our findings that TCF21 and AHR are expressed in the atherosclerotic plaque and that they interact to modulate inflammatory genes and matrix modifying genes suggest that the interaction may directly promote plaque instability leading to myocardial infarction." (PMID 28481916, 2017).
small cell lung carcinoma (8 papers, 2009 to 2025). Small cell lung cancer (SCLC) is a highly aggressive malignant neoplasm, accounting for 10-15% of lung cancer cases, characterized byrapid growth, and early metastasis. "In addition, the expression of CYP1A1 and AhR in small-cell lung carcinoma has been proposed as a putative diagnostic marker and has also been correlated with a history of cigarette smoking." (PMID 19531241, 2009). "A clinical phase I trial studying an AhR inhibitor in patients with advanced small cell lung cancer or head and neck cancer has recently been completed (NCT04069026), highlighting that AhR merits further investigation in the cancer setting." (PMID 40646277, 2025). "Moreover, upregulated SOX2 contributed to the stemness and metastasis of small cell lung cancer (SCLC) cells, while inhibition of the AhR signaling pathway blocked benzo(a)pyrene-induced protein kinase A (PKA) expression and downstream PKA/SOX2 axis." (PMID 38791215, 2024).
squamous cell carcinoma (8 papers, 2018 to 2025). A carcinoma arising from squamous epithelial cells. "We found that AHR expression was significantly lower in primary tumors compared to normal tissue in both adenocarcinoma and squamous cell carcinoma." (PMID 40303305, 2025). "AHR agonists also significantly increased migration of squamous cell carcinoma cells in culture." (PMID 32153556, 2020). "Additionally, AHR deficiency in the skin favors bacterial infection with difficulties in controlling stable skin microflora, while this lack of AHR also protects against UVB-induced cutaneous squamous cell carcinomas or skin tumorigenesis caused by Benzo[a]pyrene." (PMID 36499247, 2022). "In vitro studies showed that the aryl hydrocarbon receptor (AHR) contributed to the development of cutaneous squamous cell carcinomas, but supporting clinical data are lacking." (PMID 30144817, 2018).
age-related macular degeneration (7 papers, 2017 to 2024). Age-related loss of vision in the central portion of the retina (macula), secondary to retinal degeneration. "The AHR has also been proposed to play a potential role in the susceptibility of age-related macular degeneration (AMD), the most common cause of visual impairment in individuals over 65 years old." (PMID 32947781, 2020). "Recent studies demonstrated that AHR deficiency causes dysregulated cellular matrix metabolism and age-related macular degeneration-like pathology." (PMID 28523069, 2017). "Knock-out of AhR in mice can lead to age-related macular degeneration-like pathology, suggesting a role for AhR in protecting RPE cells from chronic environmental stress." (PMID 38635505, 2024). "A considerable role of AhR in age-related macular degeneration, glaucoma, and other eye diseases has been identified." (PMID 35743162, 2022). "This means that in age-related macular degeneration, the efficacy of melatonin is attributable to its ability to modulate the expression of AhR signaling pathway genes." (PMID 35743162, 2022). "That study implies that AhR plays a protective part in the retina as a sensor of environmental stress, whereas altered AhR function may contribute to the progression of age-related macular degeneration in humans." (PMID 35743162, 2022). "A significant role for the AHR in age-related macular degeneration (AMD), autoimmune uveitis, and other ocular diseases has been identified." (PMID 35295218, 2022). "Up-regulates AhR target genes CYP1A1 and CYP1B1 and may prevent age-related macular degeneration." (PMID 35566359, 2022).
airway hyperresponsiveness (7 papers, 2015 to 2023). "Collectively, these findings indicate that AhR in AT2 cells protects against cockroach allergen–induced airway hyperresponsiveness and Th2-associated allergic airway inflammation." (PMID 35935956, 2022). "Taken together, we used our newly generated Sftpc-Cre;AhRf/f mice and provided a strong evidence that AhR in AT2 cells protects against cockroach allergen–induced airway hyperresponsiveness and Th2-associated airway inflammation." (PMID 35935956, 2022). "In the present study, we specially focused on AT2 cells by generating AhR knockout mice in AT2 cells (Sftpc-Cre;AhRf/f) and provided supporting evidence that AhR in AT2 cells prevents allergen-induced airway hyperresponsiveness and Th2-associated airway inflammation." (PMID 35935956, 2022). "Using the newly generated Sftpc-Cre;AhRf/f mice, we found that AT2 cell–specific deletion of AhR led to an exacerbation of allergen-induced airway hyperresponsiveness and airway inflammation with elevated eosinophils and Th2 cytokines in BALFs." (PMID 35935956, 2022). "Together, the data demonstrate that ozone exposure activates AhR, which controls lung inflammation, airway hyperresponsiveness, and tissue remodeling via the reduction of IL-22 expression." (PMID 32161582, 2020). "AhR plays a protective role on lung inflammation, airway hyperresponsiveness, and tissue remodeling after chronic ozone exposure (1.5 ppm, twice a week for 2 h)." (PMID 32161582, 2020). "Next, we investigated whether the AhR regulates airway hyperresponsiveness in OVA challenged mice using a flexiVent to measure airway resistance upon exposure with increasing concentrations of aerosolized methacholine." (PMID 34744763, 2021). "IL-6, VEGFA, and AHR interact to induce eosinophilic airway inflammation, mucinous metaplasia, subepithelial fibrosis, myocyte proliferation, and dendritic cell activation, leading to airway hyperresponsiveness and angiogenesis of airway remodeling." (PMID 32015750, 2020). "These discoveries highlight the complexity of AhR activation and the need for the investigation into how AhR specifically in AT2 cells regulates airway inflammation and airway hyperresponsiveness." (PMID 35935956, 2022). "Despite not having an effect on the inflammatory response, the AhR did aggravate Cl2-induced airway hyperresponsiveness." (PMID 34744763, 2021). "Taken together, these findings suggest that TCDD-induced AhR activation prevents the development of allergen-induced non-eosinophilic airway inflammation and airway hyperresponsiveness." (PMID 26938767, 2016). "However, absence of AhR reduced Cl2-induced airway hyperresponsiveness." (PMID 34744763, 2021). "As expected, apigenin treatment reduced the expression of AhR in EDC‐augmented eosinophilic asthma mice and significantly decreased airway inflammation, type 2 cytokines, and airway hyperresponsiveness compared to mice that were not treated with apigenin." (PMID 37315181, 2023).
alcoholic liver diseases (7 papers, 2021 to 2025). A disorder caused by damage to the liver parenchyma due to alcohol consumption. "Mice deficient in AhR in intestinal epithelia suffer from severe alcoholic liver disease and gut dysbiosis when fed an ethanol diet." (PMID 38886098, 2024). "In a murine model of alcoholic liver disease, ethanol-associated dysbiosis reduced AhR activation levels, and thus intestinal Il-22 production was also decreased." (PMID 35742682, 2022). "In patients, alcoholic liver disease was associated with low levels of intestinal microbiota-derived tryptophan metabolites, underscoring the clinical impact of the AHR pathway in alcoholic liver disease." (PMID 34075438, 2021). "However, when C56BL/6 were fed an ethanol diet along with synthetic AhR agonists, the mice were protected from alcoholic liver disease." (PMID 38886098, 2024). "Given that there is no treatment that reverses alcohol-induced liver lesions except for liver transplantation, the modulation of AhR signaling by supplementation with AhR ligand-producing bacteria may hold promise in inspiring new therapeutic therapies for alcoholic liver disease." (PMID 35656117, 2022). "Altogether, these findings strengthen the functional role of AhR in regulating the PPP2R2D-AMPK axis and the resultant autophagy pathway in alcoholic liver disease." (PMID 36241614, 2022).